AGR2 (anterior gradient 2, protein disulphide isomerase family member)
Diseases named in the same sentence as AGR2 in open-access papers (continued):
Sharing a sentence is not in itself a finding about the gene and the disease.
prostate carcinoma (continued). "In prostate cancer, expression of AGR2 is increased in the tumor epithelial cells; normal luminal cells have no detectable expression." (PMID 26445321, 2015). "With this common trend, we expected cancer expression of AGR2 to be correlated with better patient survival as was demonstrated for prostate cancer." (PMID 26445321, 2015). "As already reported for other ER-resident proteins in cancer, AGR2 protein concentration has also been found increased in serum or plasma samples of ovarian, lung and prostate cancer patients compared to healthy controls." (PMID 25875093, 2015). "AGR2 is upregulated in multiple cancers, including breast, lung adenocarcinoma, ovarian, and prostate cancers." (PMID 24717913, 2014). "In prostate cancer, AGR-2 is reported to be androgen inducible and only over-expressed during early stages of carcinogenesis." (PMID 24587138, 2014). "To determine whether spliced variants exist that are specifically expressed in prostate cancers, we carried out reverse transcribed polymerase chain reaction (rt-PCR) on mRNA isolated from prostate tumor cell lines using primers in exons 1, 2 and 8 of the AGR2 gene." (PMID 25237833, 2014). "Substantial AGR-2 expression was also confirmed in prostate cancer tissue specimens in patients with bone lesions." (PMID 24587138, 2014). "The present study employed AGR-2 gene silencing method in bone metastatic human prostate cancer cell line PC3 to understand its biological function in prostate cancer bone metastasis." (PMID 24587138, 2014). "We found significant upregulation of AGR-2 expression in a bone metastatic prostate cancer cell line, PC3, following culturing in bone marrow-conditioned medium." (PMID 24587138, 2014). "In our microarray study, significant upregulation of AGR-2 mRNA expression following maintenance in bone marrow conditioned medium suggests a role of AGR-2 in facilitating the growth of prostate cancer cells in the bone microenvironment." (PMID 24587138, 2014). "By gene expression analysis, we observed significant augmentation of AGR-2 in the PC3 prostate cancer cell line, metastasized to bone, following maintenance in normal bone marrow-conditioned medium." (PMID 24587138, 2014). "To illustrate what noun phrases are, we include a passage from the paper, Differential expression of anterior gradient gene AGR2 in prostate cancer which has a PubMed ID of 21144054." (PMID 21935487, 2011). "As an example, expression of the regulator gene AGR2 we identified to be elevated in prostate cancers of aggressive phenotype was down-regulated ∼11-fold (p<0.02) following RPL19 knockdown." (PMID 21799931, 2011). "In contrast, AGR2 was a strong predictor of tumor recurrence for individuals with high stage prostate cancer." (PMID 21144054, 2010). "Similar to us, they observed an increase in AGR2 expression in prostate cancer compared to normal or benign tissue." (PMID 21144054, 2010). "AGR2 (anterior gradient 2) was one among several such genes identified as overexpressed in prostate cancer cells." (PMID 21144054, 2010). "Consistent with this, relatively lower levels of AGR2 were highly predictive of disease recurrence in patients who had originally presented with high-stage primary prostate cancer (P = 0.009)." (PMID 21144054, 2010). "To further evaluate the utility of AGR2 as a cancer biomarker, we examined the expression pattern of AGR2 in prostate cancer using both gene expression analysis and a high-density tissue microarray." (PMID 21144054, 2010). "In summary, we found that AGR2 is a secreted protein expressed at relatively high levels by prostate cancer cells and cells in PIN lesions." (PMID 21144054, 2010). "Specifically, relatively lower levels of AGR2 predicted a significantly greater chance of prostate cancer recurrence compared to higher levels (P = 0.009)." (PMID 21144054, 2010).
prostate carcinoma (continued). "PCP contains data on 359 proteins in total, including 17 potential biomarkers of prostate cancer, particularly AGR2, annexins, S100 proteins, PRO2675, and PRO2044." (PMID 22649669, 2010). "Accordingly, some studies have found AGR2 to be a marker of poor prognosis in human breast and prostate cancers." (PMID 21144054, 2010). "The differential AGR2 expression in prostate cancer prompted us to examine possible links between expression and clinical outcomes." (PMID 21144054, 2010). "We further examined the relationship of AGR2 protein expression to histopathology and prostate cancer outcome on a population basis using tissue microarray technology." (PMID 21144054, 2010). "We found that a relatively higher expression of AGR2 in patients with high stage prostate cancer stratified these individuals as less likely to have a tumor recurrence." (PMID 21144054, 2010). "In our data, the lower expression of AGR2 in higher Gleason tumors appears to correlate with AGR2 being predictive of prostate cancer recurrence in individuals with higher stage cancers." (PMID 21144054, 2010). "The related AGR2 was previously shown to be androgen-inducible and overexpressed in prostate cancer." (PMID 20021671, 2009). "Of interest, two genes involved in prostate cancer progression, androgen receptor and AGR2, are increased in prostates of Ebp1 knock out mice." (PMID 19094237, 2008). "Moreover, investigations into AGR2 expression in urine have shown promising potential for cancer detection, particularly in bladder cancers and as a specific marker for prostate cancer cells when secreted into the urine." (PMID 39062458, 2024). "Furthermore, in prostate cancer, extracellular AGR2 combines with vascular endothelial growth factor (VEGF), before activating VEGF receptor signalling and inducing angiogenesis." (PMID 36327302, 2022). "In prostate cancer cells, AGR2 promotes cell adhesion by regulating the expression of integrin." (PMID 33717413, 2021). "Additionally, AGR2 was detected in both the cell lysates and conditioned media in some cancer cell lines, or in both the carcinoma biopsies and urine exosomes of prostate cancer patients." (PMID 33413231, 2021). "Accumulating evidence suggests that AGR2 is a secretory molecule; its protein levels are found to be elevated in blood samples in several types of cancer patients and the urine of prostate cancer patients." (PMID 33413231, 2021). "AGR2 expresses strongly in prostate tissue and show increased expression in prostate cancer." (PMID 33604283, 2020). "Bone and soft tissue metastases in advanced prostate cancer show high AGR2 expression, and in pancreatic cancer, metastatic growth could be inhibited by targeting AGR2." (PMID 31303962, 2019). "AGR2 was also detected at elevated levels in the urine samples of prostate cancer patients." (PMID 31247903, 2019). "Moreover, in other types of cancer, such as prostate cancer, ovarian cancer and colorectal cancer, the prognostic value of AGR2 remains largely inconclusive." (PMID 29138453, 2017). "Interestingly, reduced cell adhesion was also observed after abrogation of AGR-2 expression in prostate cancer cells." (PMID 28810836, 2017). "Third, as a secreted protein, the significant elevation of AGR2 in pancreatic juice from pancreatic cancer patients or in urine from prostate cancer patients suggests that AGR2 may also function extracellularly during the development of cancer." (PMID 29138453, 2017). "In prostate cancer metastasis, the tumor-derived AGR2 could contribute significantly to organ failure with the destruction of normal cells." (PMID 27283903, 2016). "Bladder cancer cells, like prostate cancer cells, could be sorted into different AGR2/CD10 phenotypes for survival correlation." (PMID 26894971, 2016).
prostate carcinoma (continued). "Since AGR2 has been detected in the body fluids from cancer patients as well as in the conditioned media from pancreatic and prostate cancer cells, we hypothesized that tumor organoids may also secrete AGR2 (extracellular AGR2 / eAGR2)." (PMID 27240165, 2016). "Many prostate cancer metastases in advanced diseases also show high AGR2 expression." (PMID 27283903, 2016). "Whether AGR2+ tumor cells predominate in the late stages of bladder cancer like prostate cancer remains to be determined." (PMID 26894971, 2016). "Meanwhile, AGR2 has been described as a serum biomarker for ovarian, lung and prostate cancer." (PMID 25875093, 2015). "Although AGR2 positive primary prostate tumors were associated with better clinical outcome than AGR2 negative tumors, many distal prostate cancer metastases in bone and visceral organs showed strong immunostaining for AGR2." (PMID 26445321, 2015). "Depending on the cancer cell types, AGR2 may play roles in differentiation (as in low grade prostate tumors), cell growth and migration (as in advanced prostate cancer)." (PMID 26445321, 2015). "AGR-2 expression was also determined in bone metastatic prostate cancer tissue specimen." (PMID 24587138, 2014). "In fact, a significantly higher AGR-2 expression was observed in circulating prostate cancer cells." (PMID 24587138, 2014). "Here we investigated whether AGR2 transcript levels can be used as a biomarker to detect prostate cancer (PCa)." (PMID 25237833, 2014). "Moreover, a significantly higher odds ratio was observed between caspases-3 and AGR-2 in human prostate cancer data suggesting a strong relationship between AGR-2 and caspases-3 mediated execution steps of apoptosis." (PMID 24587138, 2014). "A multiplex ELISA to measure prostate cancer secreted proteins (e.g., AGR2 and others) could eventually be developed to complement the RNA test." (PMID 23029164, 2012). "Although the gene signatures of all forms of urogenital cancer/diseases are largely unknown, the six known prostate cancer genes of AGR2, AMACR, CRISP3, ERG, HPN, and PCA3 are at or below background, for example, in bladder cancer." (PMID 23029164, 2012). "Our group, as well as others, is also examining AGR2 as a potential prostate cancer biomarker." (PMID 21144054, 2010). "Gene expression levels of AGR2 were examined in prostate cancer cells by microarray analysis." (PMID 21144054, 2010). "We are currently exploring whether AGR2 detected in body fluids is an accurate gauge for prostate cancer initiation, progression, and/or outcome." (PMID 21144054, 2010). "We therefore hypothesize that in later stage prostate cancer, the balance towards increased proliferation (e.g., lower AGR2 expression) outweighs the need for enhanced migration and invasion (e.g., higher AGR2 expression)." (PMID 21144054, 2010). "Inhibition of AGR2 could abolish prostate cancer metastasis." (PMID 38595814, 2024). "Thus, it is likely that the structures for isoforms that are able to be secreted into the extracellular space resemble that of isoform H. This is consistent with the observation that AGR2 SV-H was the most significantly expressed isoform in urine exosomes isolated from prostate cancer patients." (PMID 31247903, 2019). "In addition to pancreatic cancer, the lysis of eAGR2+ PC3 cancer cells in vitro shows that targeting AGR2 could also prove to be effective against prostate cancer." (PMID 31303962, 2019). "Therefore, further studies on the role of AGR-2 in human prostate cancer and its downstream targets might lead to a better understanding of bone metastasis and may signify AGR-2 as a possible therapeutic target for preventing prostate cancer bone metastasis." (PMID 24587138, 2014). "Urothelial AGR2 expression was 40 times lower than prostate cancer AGR2 expression as calculated from the array signal intensity values for AGR2 in CD9+ urothelial cells and sorted CD26+ prostate cancer cells." (PMID 26894971, 2016).
prostate carcinoma (continued). "We have recently demonstrated in immunohistochemical analysis an increased expression of AGR2 in PIN lesions and in low-grade prostate cancers compared to benign tissue." (PMID 25237833, 2014). "Relative AGR-2 mRNA expression was determined in bone metastatic PC3, LnCap and C4-2B human prostate cancer cell lines and brain metastatic Du145 prostate cancer cell line by RT-PCR." (PMID 24587138, 2014). "Results indicate significantly higher AGR-2 expression in PC3, LnCap and C4-2B cell lines compared to Du145 cell line, suggesting importance of AGR-2 in prostate cancer bone metastasis." (PMID 24587138, 2014). "RNA from a dilution series of prostate cancer lines C4-2 and PC3 was prepared, and hybridized to a probe library of six selected genes: KLK3, CD90/THY1, AGR2, HPN, PCA3, UPK3A." (PMID 23029164, 2012). "In addition, AGR2 has been identified as a clinically relevant factor that modulated the behavior and response of hormone-dependent cancers such as BRCA and prostate cancer." (PMID 36405393, 2022). "The elevated level of another protein disulfide isomerase, anterior gradient 2 (AGR2), was shown to drive EMT in prostate cancer, which was accompanied by the formation of the aggressive tumor cell phenotype with increased invasive, pro-metastatic, and angiogenic potentials." (PMID 32268506, 2020). "Normal bladder non-secretion of AGR2 makes urinary AGR2 measurement a viable test to detect prostate cancer." (PMID 26894971, 2016). "In prostate cancer spread to regional lymph nodes, however, CD10 is more involved than AGR2." (PMID 26894971, 2016). "AGR-2-silenced PC3 cells showed significantly reduced cellular adhesion to fibronectin, collagen I, collagen IV, laminin and fibrinogen, which suggests AGR-2 plays an important role in prostate cancer cell attachment within the bone marrow microenvironment." (PMID 24587138, 2014). "The selected markers are those with increased expression in prostate cancer such as PCA3 and AGR2." (PMID 23029164, 2012). "In both populations, AGR2 transcript levels were significantly higher in primary prostate cancer tissue compared to non-malignant prostate." (PMID 21144054, 2010). "We have shown for the first time that despite an increase in AGR2 expression in prostate cancer compared to non-malignant cells, relatively lower levels of AGR2 are highly predictive of disease recurrence following radical prostatectomy." (PMID 21144054, 2010). "Our study has shown that AGR2 is higher in prostate cancer cells compared to non-malignant prostatic epithelial cells at the transcript and protein levels." (PMID 21144054, 2010). "To further evaluate the utility of AGR2 as a cancer biomarker, we examined the gene expression pattern of AGR2 in human prostate cancer compared to non-malignant prostatic glandular epithelium." (PMID 21144054, 2010). "PCD induced by AGR2 could also explain the absence of CD104+ basal epithelial cells in prostate tumor glands, which is a diagnostic criterion for prostate cancer." (PMID 27283903, 2016).
pancreatic cancer (45 papers, 2010 to 2025). "AGR2, a protein disulfide isomerase overexpressed in pancreatic cancer, is implicated in metastasis, chemoresistance, and endoplasmic reticulum (ER) stress adaptation." (PMID 41326375, 2025). "In pancreatic carcinogenesis, chronic ER stress leads to an inflammatory state that, along with KRAS mutations, induces AGR2 expression and contributes to pancreatic cancer development." (PMID 40459063, 2025). "Research suggests that AGR2 can function as an oncogene, with its heightened expression linked to the advancement of hepatobiliary and pancreatic cancers through invasion and metastasis." (PMID 39062458, 2024). "The GEPIA online tool was then used to evaluate the association between AGR2 mRNA expression and disease-free survival for pancreatic cancer patients." (PMID 39727484, 2024). "While the exact relationship between pancreatic cancer and AGR2 is still being clarified, overexpression of AGR2 has been linked to increased cancer cell proliferation in various types of pancreatic cancer cells." (PMID 39062458, 2024). "It was later demonstrated that C4.4A directly associates with AGR2, and a positive correlation exists between the expression of AGR2 and C4.4A in pancreatic cancer tissues." (PMID 33717413, 2021). "In searching for the underlying molecular effectors of H-1-2, we discovered that HIF1α and AGR2 mRNA were upregulated in tumor tissues of pancreatic cancer patients, both of which were previously implicated in the tumorigenesis of pancreatic cancer." (PMID 32322663, 2020). "High levels of AGR2 were also associated with cell dissemination of pancreatic carcinoma and with poor prognosis of lung cancer." (PMID 28686225, 2017). "Notably, increased AGR2 expression in pancreatic cancer cells post-chemotherapy treatment has been associated with enhanced cancer cell viability, suggesting a role of AGR2 in the development of chemo-resistance." (PMID 39062458, 2024). "The most upregulated transcript was anterior gradient 2 (Agr2), upregulated 44-fold at P2, which encodes a protein disulfide isomerase that is important for the production of mucin, but which is also a prometastatic factor for pancreatic cancer." (PMID 36232358, 2022). "Upregulation of AGR2 is associated with the initiation of cancer, and this protein can induce cell apoptosis and enhance the sensitivity of pancreatic cancer cells to chemotherapy via the extracellular signal‐regulated kinase (ERK)/serine-threonine kinase (AKT) pathways." (PMID 34632938, 2021). "AGR2 is an endoplasmic reticulum-resident protein disulfide isomerase with increased expression levels that are implicated in several cancers, including breast, ovarian, prostate, bladder, and pancreatic cancer." (PMID 29796176, 2018). "By enhancing endoplasmic reticulum folding capacity, AGR2 allows pre-cancerous cells to accommodate increased protein demand both before and after oncogenic mutations such as that of Kras, ultimately leading to pancreatic cancer progression." (PMID 29796176, 2018). "This study shows the critical role of AGR2 in ferroptosis suppression across pancreatic cancer cell lines and in vivo models." (PMID 41326375, 2025). "The expression of AGR2 is positively correlated with FPN1 in pancreatic tumor tissues, which is related to the poor prognosis of pancreatic cancer patients." (PMID 41326375, 2025).